WNT2 (Wnt family member 2)
Description:
Ligand for members of the frizzled family of seven transmembrane receptors. Functions in the canonical Wnt signaling pathway that results in activation of transcription factors of the TCF/LEF family. Functions as a upstream regulator of FGF10 expression. Plays an important role in embryonic lung development. May contribute to embryonic brain development by regulating the proliferation of dopaminergic precursors and neurons (By similarity).
Synonyms: IRP; INT1L1
Tractability: Antibody: UniProt places it where antibodies can reach, with high confidence; its Gene Ontology location is reachable by antibodies, with high confidence; UniProt predicts a signal peptide or a membrane-spanning region.
Target class: Secreted protein
Gene: Protein-coding gene on chromosome 7 (117,275,451 to 117,323,152, reverse strand). Ensembl gene ENSG00000105989.
Subcellular location: Secreted, extracellular space, extracellular matrix; Secreted
Subcellular location (Human Protein Atlas): Vesicles; Predicted to be secreted
Pathways (Reactome):
Signal Transduction: Class B/2 (Secretin family receptors); WNT ligand biogenesis and trafficking
Gene Ontology:
Molecular function: cytokine activity; frizzled binding; protein binding; receptor ligand activity; signaling receptor binding
Biological process: canonical Wnt signaling pathway; cell proliferation in midbrain; cell-cell signaling; cellular response to transforming growth factor beta stimulus; mammary gland epithelium development; midbrain dopaminergic neuron differentiation; positive regulation of cell population proliferation; positive regulation of fibroblast proliferation; positive regulation of transcription by RNA polymerase II; cell fate commitment; cellular response to retinoic acid; iris morphogenesis; lens development in camera-type eye; neurogenesis; neuron differentiation; animal organ development; positive regulation of neurogenesis; system development; Wnt signaling pathway
Cellular component: cytoplasm; extracellular matrix; extracellular region; Wnt signalosome
Genetic constraint (gnomAD): Loss-of-function variants: 12 observed, 38.03 expected, observed/expected ratio (o/e) 0.32, 90% interval 0.2 to 0.51. The upper end of that interval is the gene's LOEUF score, 0.51, which puts it in group 2 of 6, group 1 being the genes least tolerant of losing a copy. Missense variants: 379 observed, 499.25 expected, observed/expected ratio (o/e) 0.76, 90% interval 0.7 to 0.83. Synonymous variants: 163 observed, 183.86 expected, observed/expected ratio (o/e) 0.89, 90% interval 0.78 to 1.01.
Homologues: Orthologues: chimpanzee WNT2 (99% identical), macaque WNT2 (99% identical), mouse Wnt2 (96% identical), guinea pig WNT2 (95% identical), pig WNT2 (95% identical), rabbit WNT2 (94% identical), rat Wnt2 (93% identical), dog WNT2 (90% identical), tropical clawed frog wnt2 (76% identical), zebrafish wnt2 (67% identical), Drosophila melanogaster Wnt5 (43% identical), Caenorhabditis elegans cwn-2 (41% identical), and 4 more. Paralogues in human: WNT2B (68% identical), WNT5A (48% identical), WNT5B (46% identical), WNT4 (45% identical), WNT3 (44% identical), WNT7A (43% identical), WNT3A (43% identical), WNT7B (43% identical), WNT16 (41% identical), WNT1 (41% identical), WNT10B (38% identical), WNT6 (38% identical), and 6 more.
Diseases named in the same sentence as WNT2 in open-access papers:
WNT2 is named in the same sentence as 142 diseases in open-access papers, as found by Europe PMC text mining. Sharing a sentence is not in itself a finding about the gene and the disease. The quoted sentences say what the papers report.
colorectal cancer (37 papers, 2009 to 2025). A primary or metastatic malignant neoplasm that affects the colon or rectum. "For instance, the upregulation of WNT2 in colorectal cancer was mechanistically linked to a decrease in repressive histone mark H3K27me3." (PMID 38474826, 2024). "For example, Wnt2 expression can be upregulated in colorectal cancer via loss of repressive histone mark H3K27me3 by EZH2." (PMID 34552611, 2021). "WNT2 expression has been significantly associated with cancer development in pancreatic cancer, gastric cancer, colorectal cancer, cervical carcinoma, and non-small cell lung cancer." (PMID 34287269, 2021). "A previous study reported that cancer associated fibroblasts secrete Wnt2 to promote progression in colorectal cancer." (PMID 34901211, 2021). "A recent study indicated that high Wnt2 expression in fibroblasts is associated with poor prognosis in human colorectal cancer." (PMID 30814912, 2019). "It has been reported in the literature that WNT2 is overexpressed in colorectal cancer, cervical cancer, human fibroadenomas, pancreatic cancer, and breast cancer, thereby triggering migration and invasion." (PMID 40576246, 2025). "Background and Objectives: We aimed to investigate the role of Wnt2 expression in colorectal cancer (CRC) prognosis and evaluate its potential as a therapeutic target in BRAF-mutated CRC." (PMID 37374338, 2023). "Human WNT2 is commonly upregulated in primary gastric and colorectal cancer and less frequently upregulated in primary breast cancer." (PMID 36476410, 2022). "In case of colorectal cancer, miR-548b overexpression can suppress cell proliferation by targeting Wnt2." (PMID 34552611, 2021). "In colorectal cancer, including the spectrum from normal colorectal adenoma to cancer, infiltrating macrophages display high levels of Wnt2 and Wnt5a." (PMID 34579753, 2021). "For example, WNT2 overexpression in colorectal cancer and hepatocellular carcinoma indicates poor prognosis." (PMID 34565373, 2021). "For example, WNT10B is downregulated in colorectal cancers as a result of promoter hypermethylation and, on the contrary, WNT2 is upregulated due to histone modifications." (PMID 33189141, 2020). "In human colorectal cancer (CRC), WNT2 is selectively elevated in cancer-associated fibroblasts (CAFs), leading to increased invasion and metastasis." (PMID 31667643, 2020). "Among these ligands, Wnt2 plays the main role in the tumorigenesis of several human cancers especially colorectal cancer (CRC)." (PMID 33224221, 2020). "Studies have shown that Wnt2 protein is the main regulator of Wnt signaling pathway and its overexpression has been detected in various types of cancer, especially colorectal cancer." (PMID 33224221, 2020). "In a next step, we evaluated xenograft experiments with WNT2 overexpressing HCT116 colon cancer cells that we recently published on the role of WNT2 as a driver in colorectal cancer progression to investigate the in vivo relevance of our findings." (PMID 31667643, 2020). "Wnt2 is overexpressed in many stages of the development of colorectal cancer, and Wnt5a is overexpressed in breast cancer, colorectal cancer, lung cancer, prostate cancer and melanoma." (PMID 33310972, 2020). "Wnt2 mRNA overexpression has been reported in fibroadenomas, breast cancers, and colorectal carcinomas." (PMID 32983993, 2020). "In colorectal cancer, the infiltrating macrophages express high levels of Wnt2 and Wnt5a in progression from normal colorectal adenoma to carcinoma." (PMID 31921137, 2019). "CAFs are also considered to be a main source of Wnt2 in colorectal cancer where FZD8 acts as a putative receptor of Wnt2 and is responsible for tumor growth, invasions, and metastasis." (PMID 31921137, 2019). "Monoclonal antibodies (MAbs) designed to bind Wnt1 and Wnt2 have shown to lead to tumor suppression in a plethora of malignancies, including, but not limited to, melanoma, colorectal cancers, and non-small cell lung carcinoma." (PMID 31921137, 2019).
colorectal cancer (continued). "Wnt2 enhances colorectal carcinomas’ angiogenesis and extracellular matrix remodelling." (PMID 38136392, 2023). "Wingless-type MMTV integration site family member 2 (WNT2), a protein that leads to autocrine activation of the Wnt/β-catenin pathway, is upregulated in CAFs and promotes angiogenesis, resulting in promoting colorectal cancer growth in vivo." (PMID 35327514, 2022). "In addition, overexpression of Wnt2 mRNA was detected to exert an indispensable effect on disease processes, such as colorectal polyps, primary colorectal cancer, and the liver metastasis of colorectal cancer." (PMID 35356220, 2022). "Specific Wnt ligands and receptors are found to be overexpressed in many tumors; monoclonal antibodies developed against Wnt-1 and Wnt-2 demonstrate Wnt inhibition leading to tumor suppression in melanoma, sarcoma, colorectal cancers, non-small cell lung carcinoma, and mesothelioma." (PMID 33607955, 2021). "In previous studies, Wnt2 gene expression has been verified to be significantly high in the stroma of colorectal carcinoma patients compared with that in the stroma of normal patients; moreover, it promotes cancer cell metastasis and invasion through the Wnt signaling pathway." (PMID 32983993, 2020). "Consistent with our findings, previously reported findings suggest that WNT2 expression in human colorectal carcinoma and esophageal cancer may also have a biological function." (PMID 27513465, 2016). "Here we found that Wnt2 is highly expressed in colorectal cancer (CRC) cells." (PMID 26484565, 2015). "Besides the APC gene, which occurs in over two-thirds of colorectal cancer, WNT2 and MACF1 also impact the Wnt pathway, while RASA1 is in the RAS pathway." (PMID 25974029, 2015). "Notably, Wnt2 is overexpressed in human colorectal carcinomas but only up-regulated in a small subset of prostate cancer, but is overexpressed in primary NSCLC and plays a role as mediator of apoptosis in several cancers of epithelial origin." (PMID 19812696, 2009). "However, emerging evidence suggests that WNT-2 secreted by CAFs may inhibit the differentiation and activation of dendritic cells, facilitating immune evasion by esophageal squamous cell carcinoma and colorectal cancer." (PMID 36506313, 2022). "COL8A1 may affect the progression of colorectal cancer and the prognosis of patients by regulating focal adhesion-related pathways, and the expression of COL8A1 in colorectal cancer is related to the expression of Wnt2 and is linked to the poor survival of patients." (PMID 35774273, 2022).
breast carcinoma (18 papers, 2011 to 2025). "Previous studies have shown upregulated Wnt2 in the primary breast tumor is linked to metastatic disease, and more recently, Wnt2 was identified as a regulator of tumor initiation in a basal-like breast cancer model." (PMID 30458886, 2018). "In this study, we have highlighted the significance of TGFβ-1, IL19, CXCR4, BMP1, IL1A, VCAN, PDK1, and WNT2 in breast cancer pathology." (PMID 41348904, 2025). "By employing UALCAN, we examined the pattern of expression for TGFβ-1, IL19, CXCR4, BMP1, VCAN, and WNT2 in breast cancer." (PMID 41348904, 2025). "bacciferum's ethanolic extract have been demonstrated in MCF-7 cells by modulation of apoptosis signalling molecules like Wnt2, GSK3β, and β-catenin in human breast cancer cells." (PMID 38800305, 2024). "bacciferum suppressed the GSK3β and Wnt2 signaling pathways in MCF-7 breast cancer cell lines, acting as an anti-metastatic and anticancer agent." (PMID 38800305, 2024). "H. bacciferum plant extract significantly inhibited the growth of breast cancer cells by modulating GSK3β, Wnt2, and β-catenin signaling, indicating that H." (PMID 38800305, 2024). "METABRIC analysis of several Wnt signaling targets overexpressed in breast cancer revealed that Wnt2 and Frizzled 9 (Fzd9) were inversely correlated with IGF-1R expression in humans." (PMID 30458886, 2018). "Previous studies also found that the ectopic expression of Wnt2 plays an important role in the proliferation, invasion, and migration of breast cancer." (PMID 28665975, 2017). "The expression pattern of TGFβ-1, IL19, CXCR4, BMP1, VCAN, and WNT2 in different molecular subclasses of Breast Cancer revealed that TGFβ-1, IL19, CXCR4, BMP1, VCAN, and WNT2 mRNA levels are higher in luminal A followed by luminal B, HER2 and Basal-like respectively." (PMID 41348904, 2025). "The upregulation of WNT2 mRNA in breast cancer happens through estrogen." (PMID 36476410, 2022). "Furthermore, elevated WNT2 expression is a common feature in breast carcinomas and breast cancer cell lines." (PMID 21542898, 2011). "We compared the TGFβ-1, CXCR4, IL19, BMP1, VCAN, and WNT2 expression in different subtypes of breast cancer, and the results demonstrated that BMP1, and WNT2 were consistently overexpressed in HER-2 subtype." (PMID 41348904, 2025). "Clinicopathological analysis revealed marked upregulation of WNT2 and WNT7B in HER2-positive breast cancer, suggesting a potential synergy between WNT signaling and HER2-driven oncogenic pathways." (PMID 41044153, 2025). "The highest frequency rate of “amplification” of WNT2, WNT7B, and WNT11 was recorded at 3.69%, 15.83%, and 33.25%, respectively, notably within The Metastatic Breast Cancer Project (Provisional, December 2021)." (PMID 41044153, 2025). "Expression levels of these genes were also examined across various pathological stages of breast cancer, where a stage-dependent increase was observed particularly for CXCR4, BMP1, VCAN, and WNT2." (PMID 41348904, 2025). "Eight of these genes (except WNT2, GADD45B, FZD2, WNT7B, POLK, and PIK3R3) have been extensively studied in breast cancer." (PMID 32818022, 2020). "The differential drug sensitivity of WNT2, WNT7B, and WNT11 suggests that these genes may serve as predictive biomarkers for therapeutic responses in breast cancer." (PMID 41044153, 2025).
pancreatic cancer (16 papers, 2015 to 2025). "A recent study in a pancreatic cancer mouse model used single-molecule RNA sequencing of CTCs to identify Wnt2 as an up-regulated gene in pancreatic cancer CTCs, which is implicated in cell-death suppression and cancer dissemination." (PMID 28626429, 2017). "In pancreatic cancer, direct Wnt pathway activation by upregulation of Wnt family member 2 (WNT2) and Wnt family member 7A (WNT7A) has frequently been observed, resulting in poor clinical outcomes." (PMID 36765639, 2023). "The continuous activation of the Wnt pathway and the overexpressions of canonical Wnt ligands (Wnt2, Wnt5a, and Wnt7a’s) are also observed in pancreatic cancer." (PMID 35686109, 2022). "The PDACEV signature calculated as the unweighted sum of EGFR, EPCAM, MUC1, GPC1, and WNT2 signals showed an 86% sensitivity and 81% specificity in distinguishing pancreatic cancer patients from healthy controls." (PMID 33803470, 2021). "Their additional functional experiments showed that Wnt2 promotes anchorage-independent cell survival and the metastatic potential of pancreatic cancer cells." (PMID 27414409, 2016). "Heatmap analysis in colorectal, stomach, and pancreas cancer patient datasets showed a consistent overlap between LBH overexpression and WNT signaling genes associated with pathway activation, i.e., WNT2, WNT5A, WNT11, LEF1, TCF4 or TCF7, CCTNB1, CCND1, JUN, DKK3." (PMID 37268816, 2023). "Wnt2 plays an important role in the metastasis of pancreatic cancer." (PMID 28678795, 2017). "It was shown that Wnt2 is enriched in circulating pancreatic cancer cells." (PMID 26484565, 2015). "It was shown that Wnt2 plays tumorigenic roles in several cancers including non-small-cell lung cancer, pancreatic cancer, ovary cancer, esophageal cancer, and gastro-intestinal cancer." (PMID 26484565, 2015).
gastric cancer (15 papers, 2018 to 2024). A primary or metastatic malignant neoplasm involving the stomach. "For instance, neutralizing mAbs against Wnt2 and Wnt3A were shown to exert anti-proliferation effects in gastric cancer and prostate cancer models respectively." (PMID 39010070, 2024). "Immunohistochemistry assays have confirmed that WNT2 was positively expressed only in gastric cancer tissues." (PMID 38952556, 2024). "Aberrant activation of the canonical WNT pathway is considered an essential early event in the colorectal carcinogenesis, and overexpression of WNT2 has been reported in esophageal, colorectal and gastric cancers." (PMID 34274970, 2021). "DKK-1, 15 μmol/L Wnt/β-catenin signal pathway inhibitor, was added to gastric cancer cells for 48 h to detect cell proliferation and apoptosis, as well as Wnt2, p-GSK-3β, and β-catenin protein expressions." (PMID 32904598, 2020). "Next, we performed wound healing and migration assays and found that GSK3β, LRP6, or Wnt2 knockdown significantly abolished M hyorhinis‐induced gastric cancer cell motility, but the effect of Wnt2 ablation was less robust than that of the other two factors." (PMID 31321908, 2019). "In fact, high expression of WNT2 is a negative prognostic factor, which associates with the invasive/metastatic behavior of gastric-cancer cells, via stimulation of the EMT (Epithelial-to-Mesenchimal-Transition) process." (PMID 37951921, 2023). "In addition, CD44, Wnt2, Bmi1, Notch1, Oct4, Sox2, Nanog, C-mys, ABCG2, CXCR4 and other “stemness associated genes” are highly expressed in the CD44+ gastric cancer cell population." (PMID 36316684, 2022). "This was supported by independent reports on WNT2 function in esophageal and gastric cancer." (PMID 31667643, 2020). "Collagen type X alpha 1 (COL10A1) activates the WNT2-mediated Wnt pathway and promotes the development of gastric cancer, and the vast majority of patients with high expression of WNT2 have cancer in TNM Stage III or IV with lymph node metastasis, it may be a marker for patients with advanced GC." (PMID 38952556, 2024). "Emerging evidence has demonstrated that Wnt/β‐catenin is activated after gastric cancer and plays a critical role in promoting invasion and migration through overexpressing or increasing the functions of several components of the Wnt pathway such as Wnt1, Wnt2, Wnt3, Wnt5a, Fzd‐3, CTNNB1 and LRP6." (PMID 28994231, 2018). "Ligands such as Wnt2, WNT5A, and WNT10B are involved in the EMT in gastric cancer." (PMID 38952556, 2024). "Also, we found that CAF2 up-regulated Wnt signaling pathway genes such WNT2 and WNT5A while down-regulating the expression of Wnt signaling inhibitor SFRP1, which was consistent with findings from the research on CAFs for gastric cancer." (PMID 39256364, 2024). "WNT2 is one of the proto-oncogenes with the potential to activate the WNT-β-catenin-TCF signaling pathway; it promotes cell migration and invasion on the progression of gastric cancer." (PMID 31340453, 2019). "Thus, Wnt2, as a ligand of LRP6 in β‐catenin signaling, has a less important role in M hyorhinis‐induced gastric cancer cell motility." (PMID 31321908, 2019). "Thus, WNT2 and EMT activation may be factors involved in the sensitivity of gastric-cancer cells to ATRA." (PMID 37951921, 2023).